TSLP (thymic stromal lymphopoietin)
Diseases named in the same sentence as TSLP in open-access papers (continued):
Sharing a sentence is not in itself a finding about the gene and the disease.
allergic asthma (continued). "In another study, Treg cells were isolated from BALF samples in allergic asthmatic, healthy control, and nonallergic asthmatic subjects to evaluate the influence of TSLP on immunosuppressive activities of Treg cells and its potential consequences in human allergic asthma." (PMID 33748292, 2021). "Thus, therapies targeting Type 2 signaling, such as monoclonal antibodies directed against IL-13, IL-5, IL-33, TSLP (thymic stromal lymphopoietin) or their receptors, or against IgE, have been effective in treating allergic asthma without inducing a substantial cost in parasite clearance." (PMID 34899381, 2021). "Although studies have reported that CXCR2 ligands promote lung-homing of EPC and that IL-25 and thymic stromal lymphopoietin (TSLP) may promote angiogenic responses, mechanisms that orchestrate lung accumulation of EPC in allergic asthma have not been fully investigated." (PMID 25279605, 2014).
eosinophilia (53 papers, 2007 to 2025). "The authors also discuss associations with male gender, increasing age, and eosinophilia, which are suggested to be linked with higher concentrations of TSLP in the blood." (PMID 38731070, 2024). "Postnatal skin-specific inactivation of both RXRα and RXRβ (RXRs) leads to the development of an AD-like disease characterized by partial hair loss, Th2 inflammation, eosinophilia, elevated TSLP epidermal secretion, and high TSLP serum levels." (PMID 20174635, 2010). "Plasma CCL26 levels may be a useful biomarker for eCRSwNP because they are associated with NP tissue eosinophilia and plasma TSLP and IL-33 levels in patients with eCRSwNP." (PMID 40919679, 2025). "Targeting upstream alarmins—through agents such as itepekimab (anti-IL-33) and anti-TSLP antibodies—shows promise in mitigating tissue eosinophilia and broad inflammatory cascades before they fully develop." (PMID 40732309, 2025). "STAT5 signaling, particularly in response to TSLP, has a crucial role in promoting Th2-mediated inflammation and eosinophilia, whereas MYB promotes T cell differentiation and hematopoietic cell proliferation." (PMID 40470207, 2025). "IL-37 secretion was inhibited in patients with eCRSwNP, resulting in TSLP production in NECs and increased eosinophilia." (PMID 40919679, 2025). "Both anti-TSLP therapies demonstrated attenuation of allergen-induced inflammation after allergen challenge, as measured by sputum eosinophilia and fractional exhaled nitric oxide (FeNO)." (PMID 38672419, 2024). "TSLP, IL-5, IL-13 and IL-25 are the major proinflammatory cytokines that mediate eosinophilia-dominated type-2 inflammation." (PMID 37377967, 2023). "Mouse model studies suggest that eosinophilia and basophilia are promoted through TSLP-mediated upregulation of CD34+ progenitor cells and their recruitment at sites of infections." (PMID 36311787, 2022). "Overall, these data suggest that TSLP can directly modulate T lymphocytes, leading to downstream T2 inflammation and airway eosinophilia." (PMID 35572064, 2022). "The relevant pathogenic role of TSLP in eosinophilic inflammation is further corroborated by the correlation between TSLP immunoreactivity and airway eosinophilia, detected in bronchial biopsies from asthmatic patients 24 hours after allergen challenge." (PMID 33922072, 2021). "Genetic modification of collagen XVII additionally induces eosinophilia and keratinocyte expression of thymic stromal lymphopoietin (TSLP)." (PMID 34899732, 2021). "It was found that the mice treated concomitantly with TSLP and OVA showed significantly more pronounced airway inflammation and eosinophilia compared to mice receiving TSLP alone." (PMID 34301307, 2021). "Another important mechanism for TSLP-mediated eosinophilia in skin and the bronchial airway is probably due to the local production of the eosinophil chemokine eotaxin-2 by TSLP-activated DCs." (PMID 33203095, 2020). "By contrast, only 15% of COPD patients and 0% in the control group had elevated sputum eosinophilia with high periostin and TSLP levels at the same time." (PMID 33203095, 2020). "TSLP–TSLPR interactions are crucial to the development of eosinophilia and basophilia in mice; however, its role in humans is unclear." (PMID 25400924, 2014). "Transgenic expression of TSLP in mice leads to perivascular leukocytic infiltration with prominent eosinophilia, with increased severity noted in female mice compared to malemice." (PMID 22973903, 2012). "Mice immunised with gp140:TSLP or gp140:alum had significantly more eosinophilia than the other groups." (PMID 22057556, 2012). "Furthermore, TSLP expression has been found to correlate with eosinophilia and the severity of CRSwNP symptoms." (PMID 40919679, 2025).
eosinophilia (continued). "Serum miR-1 levels were inversely correlated with tissue eosinophilia in samples from patients with CRSwNP, and miR-1 recruited TSLP (and P-selectin, CCL26 [eotaxin-3], and thrombopoietin receptor) to the RNA-induced silencing complex and downregulated these genes." (PMID 40919679, 2025). "Immune factors leading to eosinophilia, including the constitutive production of IL-25/IL-33/TSLP by epigenetically modified airway epithelial cells may be less influenced by ETI and may remain constant." (PMID 37525180, 2023). "However, several other inflammatory pathways have been shown to support eosinophilia, including IL-13, and most recently, the alarmin cytokines TSLP and IL-33." (PMID 33917396, 2021). "However, several other inflammatory pathways have been shown to support eosinophilia, including IL-13, the alarmin cytokines TSLP and IL-33, and the IL-3/5/GM-CSF axis." (PMID 33917396, 2021). "In the asthmatic EMTU, the epithelial release of inflammatory cytokines (CCL-5, IL-1α, TNF-α, IL-8, and IL-6) can regulate mesenchymal inflammation to cause eosinophilia and TH2 inflammation (TSLP, GM-CSF) as well as neutrophilic inflammation (TNF-α, IL-8, IL-6)." (PMID 32679790, 2020). "Furthermore, under allergic stimulation, animals with neonatal LPS treatment exhibited normal breathing patterns and IL-4 and TSLP levels, but a lower eosinophilia as compared with control group." (PMID 32379832, 2020). "The observation that TSLP could induce eosinophilia in a model of allergy airway disease is consistent with previous studies demonstrating that i.n. immunisation every other day for 2 weeks using 0.5 μg TSLP plus OVA induced allergic airway disease." (PMID 22057556, 2012). "Nevertheless, by analogy with dupilumab-induced IL-4/13 blockade, the persistence of sputum eosinophilia (reported in both patients) raises questions as to whether TSLP inhibition could lead to a rebound of eosinophilia and potentially to eosinophil-related symptoms in patients with EGPA." (PMID 38992639, 2024). "Therefore, we examined whether TSLP, IL-25 and/or IL-33 contribute to induction of eosinophilia in the BAL fluid of mice after inhalation of large-size chitin (70–100 μm)." (PMID 33723298, 2021). "Similarly, TSLP levels have been shown to be significantly increased in CRSwNP nasal mucosa compared to CRSsNP and control nasal mucosa; and furthermore positively associated with markers of TH2 responses and eosinophilia." (PMID 31768185, 2019). "Alarmins such as thymic stromal lymphopoietin (TSLP), IL-25 (IL-17E), and IL-33 stimulate type 2 ILC secretion of IL-5 to create eosinophilia." (PMID 37587450, 2023). "The largest network of eosinophilia contained two genes (IL4R, TSLP) targeted by drugs currently available for eosinophilic asthma." (PMID 37186423, 2023). "Similar to Il33−/− mice, Il25−/− mice and Crlf2−/− mice showed attenuated airway eosinophilia after FAP inhalation, suggesting that IL-25 and TSLP, in addition to IL-33, are involved in FAP-induced airway eosinophilia." (PMID 30575775, 2018). "TSLP has been demonstrated to promote the production of eotaxin-1 by nasal epithelial cells from CRSwNP patients via the JAK-STAT3 pathway, thereby contributing to eosinophilia and inflammation." (PMID 39940994, 2025). "Levels of IL-4, IL-13, chemokine ligand 18 (CCL18), and thymic stromal lymphopoietin (TSLP) have been found to be elevated in AA scalp lesions, with levels of IL-4, IL-5, IL-6, CCL17, and immunoglobulin E (IgE) elevated and eosinophilia more prevalent in the serum/blood of patients with AA." (PMID 38022501, 2023). "We found that two-thirds of mild-to-moderate atopic asthma patients who were not treated with ICC had IS eosinophilia together with relatively high IS periostin and TSLP levels." (PMID 33203095, 2020).
eosinophilia (continued). "TSLP-activated dendritic cells produce TH2-attracting chemokines and then induce TH2 cell activation, initiating allergic inflammation by triggering IgE production, eosinophilia, and mucus production." (PMID 20064775, 2010). "Eosinophilia in curcumin-treated mice was markedly reduced, co-stimulatory molecule expression (CD80, CD86, and OX40L) on antigen-presenting cells was decreased, and expression of MMP-9, OAT, and TSLP genes was also attenuated." (PMID 17254346, 2007). "Moreover, our study suggested the novel idea that the possible combination of elevated TSLP levels and reduced tryptase levels might result in ongoing eosinophilia and non-responsiveness to high-dose ICS treatment." (PMID 33875671, 2021). "Treatment of IL5Tg mice with IL-33, but not IL-25 or TSLP, also induced a synergistic increase in bronchoalveolar lavage (BAL) eosinophilia." (PMID 33974563, 2021). "Whereas IL-33, IL-25 and thymic stromal lymphopoietin (TSLP) are involved in induction of FAP-induced ILC-mediated airway eosinophilia, IL-33—rather than IL-25 and/or TSLP—was critical for the eosinophilia in our model." (PMID 30575775, 2018).
Pruritus (49 papers, 2015 to 2025). Pruritus is an itch or a sensation that makes a person want to scratch. "Recently, several cytokines, including TSLP, IL-4/13, and IL-31, have been reported to be involved in AD-associated pruritus, and biological agents targeting these cytokines have been shown to improve pruritus in AD patients." (PMID 38590314, 2024). "TSLP causes pruritus and skin thickening in the pathogenesis of AD." (PMID 38247218, 2024). "Apart from this, TSLP is also important for promoting wound-induced hair growth and regeneration in mice, which may be an issue that should be considered to use TSLP antagonists for pruritus accompanied by hair loss." (PMID 36077340, 2022). "Future studies should explore the relationship between SERPINB3/4 and other clinical parameters, such as itch mediators (e.g., IL‐31, TSLP) and neuronal activation markers, to better understand its role in pruritus." (PMID 40995892, 2025). "Several cytokines, including TSLP, IL-13, IL-31, and IL-4, are involved in pruritus, one of the most prominent features of AD." (PMID 40429704, 2025). "These pathways include cytokines, such as IL-4, IL-13, IL-31, and TSLP, and chemokines, such as CCL1, CCL13, and CCL17, which have been implicated in barrier disruption, pruritus, and immune cell recruitment in AD." (PMID 41583462, 2025). "Thymic stromal lymphopoietin (TSLP) produced by keratinocytes and mast cells, contributes to pruritus by acting on the TSLP receptor on the sensory nerve fiber and activating TRPA1." (PMID 41166019, 2025). "Concerning pruritus in AD, injecting TSLP into the skin of mouse cheeks triggers scratching behavior dependent on IL-7Rα and primary afferent neurons." (PMID 38590314, 2024). "Basophils, activated and recruited by inflammatory mediators like thymic stromal lymphopoietin (TSLP) produced by epithelial cells, release IL-4, promoting the differentiation of naïve T cells into Th2 cells and contributing to pruritus in AD." (PMID 39126010, 2024). "The researchers also identified a specific subset of sensory neurons that require functional TSLP receptors and the ion channel TRPA1 to facilitate TSLP-evoked itch." (PMID 37834183, 2023). "Together with IL-33, TSLP, and histamine, they trigger the sensation of pruritus either directly on the sensory neurons or by modulating the neural transmission, thereby contributing to chronic itch." (PMID 37108720, 2023). "For example, in dermatitis herpetiformis, skin-derived TSLP was shown to correlate with the intensity of pruritus." (PMID 37555911, 2023). "The TSLP and IL-13, which are key factors in AD's pathogenesis, mediate pruritus, the main AD symptom." (PMID 37790739, 2023). "Lee found that skin dryness relied on TRPV4 channels to induce TSLP production in KCs and promote pruritus." (PMID 37705977, 2023). "TSLP, an epidermal alarmin produced in response to proinflammatory stimuli, amplifies pruritus in AD-specific conditions." (PMID 37958804, 2023). "JAK/STAT-mediated production of cytokines including IL-4, IL-13, IL-31, and TSLP inhibits the expression of important skin barrier proteins and triggers pruritus in AD." (PMID 35889539, 2022). "Histamine, IL-33, IL-31, IL-4, IL-13, and thymic stromal lymphopoietin (TSLP) have been suggested to be mediators of pruritus in AD." (PMID 35163297, 2022). "Substance P, IL-2, calcitonin gene-related peptide (CGRP), OPRM, and OPRK are involved in psoriasis-related itch, while thymic stromal lymphopoietin (TSLP), CGRP, IL-4, IL-13, and IL-31 are associated with AD pruritus." (PMID 35628327, 2022). "Further it was evidenced that both functional TSLPRs and TRPA1 channels are required for TSLP-induced pruritus." (PMID 33681256, 2021). "In this study, we therefore aimed to investigate the putative interactions between TSLP and TRPV4, specifically in the keratinocytes, peripheral sensory neurons, and mast cells, for elucidating the mechanisms underlying dry skin-induced pruritus." (PMID 34925342, 2021).
Pruritus (continued). "After TSLP is secreted in the keratinocytes, nerve fibers expressing TSLP receptors are activated and transmit pruritus signals to the dorsal root ganglion of the spinal cord." (PMID 33113783, 2020). "Certain cytokines, such as interleukin (IL-) 17, IL-33, IL-31, and thymic stromal lymphopoietin (TSLP), play an important role in the development of pruritus." (PMID 32454868, 2020). "TRPA1 (transient receptor potential) is required for TSLP-induced activation of sensory neurons that lead to pruritus." (PMID 30304837, 2018). "We found that TRPV3 and TSLP were increased in burn-scar tissues, especially in burn scars with pruritus." (PMID 29140280, 2017). "Increased expression of KLK5 (as seen in AD) augments PAR-2 (protease activated receptor-2) activation, which is directly related to TSLP and IL-8 induction, resulting in epidermal inflammation and pruritus." (PMID 26717000, 2015). "In psoriasis, pruritus involves Substance P, IL-2, calcitonin gene-related peptide (CGRP), μ-opioid receptors (OPRM), and κ-opioid receptors (OPRK), while in AD pruritus is linked to thymic stromal lymphopoietin (TSLP), CGRP, IL-4, IL-13, and IL-31." (PMID 39859462, 2025). "In particular, TSLP, an epithelial cell-derived cytokine, is known to activate dendritic cells and promote Th2 polarization, while IL-31 is directly involved in the induction of pruritus and skin barrier disruption." (PMID 40959436, 2025). "Furthermore, IL-4 and IL-13, together with IL-31 and thymic stromal lymphopoietin (TSLP) are involved in pruritus, whereas Th2-released IL-5 activates eosinophils." (PMID 38975347, 2024). "Additionally, TSLP released by keratinocytes acts directly on a subset of sensory neurons to trigger robust itch behaviors in animal models." (PMID 37238750, 2023). "TSLP is held to be involved in the pathogenesis of pruritus in various dermatological diseases." (PMID 37555911, 2023). "In addition, compared with normal tissues, the expression of TRPV3 and TSLP in KCs in burn scars was upregulated, especially in burn scar tissues with pruritus." (PMID 37705977, 2023). "Moreover, TRPV3 plays a dominant role in HDM-mediated itch via a PAR2/TRPV3/TSLP pathway in keratinocytes." (PMID 36385768, 2022). "TSLP involved is involved in not only Th2 cell maturation but also itch elicitation." (PMID 34065200, 2021). "However, the mechanism behind the TSLP-induced pruritus remains to be elucidated in further experimental studies." (PMID 33681256, 2021). "Based on the results of previous studies, we presumed that TSLP may be involved in dry skin-induced pruritus." (PMID 34925342, 2021). "TSLP and IL-31 stimulate sensory skin neurons involved in the pathomechanism of pruritus." (PMID 30304837, 2018). "The PAR-2-mediated TSLP production occurs pruritus and Th2 immune response in AD25,26." (PMID 30093649, 2018). "TSLP secreted by keratinocytes may acts directly on TSLP receptors on sensory nerve terminals to induce pruritus." (PMID 29140280, 2017). "Conclusively, TRPV3 may contribute to pruritus in burn scars through TSLP, and can be considered a potential therapeutic target for post-burn pruritus." (PMID 29140280, 2017). "Furthermore, TSLP is known to be relevant to cutaneous pruritus by interacting with STATs pathways." (PMID 37689763, 2023). "In addition, keratinocytes under the influence of various factors, such as exposure to allergens, microbial action, scratching resulting from pruritus—the main symptom of AD, react by releasing cytokines important for inflammation, including TSLP (thymic stromal lymphopoetin), IL-33, and IL-25." (PMID 30304837, 2018). "Therefore, upregulation of the TRPV3 channel in the scar tissue with pruritus may lead to an increase in TSLP expression, which may be one of the mechanisms of post-burn pruritus." (PMID 29140280, 2017). "Further studies have shown that the synergistic effect of TSLP and PAR2 is particularly important in mediating pruritus signal transduction." (PMID 37705977, 2023).